FOXN3 (forkhead box N3)
Diseases named in the same sentence as FOXN3 in open-access papers (continued):
Sharing a sentence is not in itself a finding about the gene and the disease.
glioma (continued). "Furthermore, gain of function and loss of function researches were applied to explore effects of FOXN3 on the proliferation, colony formation and motility capabilities of glioma cells." (PMID 34511432, 2021). "Besides, Kaplan-Meier survival curve was adopted to analyze the link between FOXN3 mRNA expression and overall survival time of glioma patients." (PMID 34511432, 2021). "Additionally, tumor transplantation model assay was performed to determine the effects of FOXN3 over-expression on glioma cell growth in vivo." (PMID 34511432, 2021). "Additionally, tumor xenograft assays revealed that FOXN3 over-expression retarded glioma cell growth in vivo." (PMID 34511432, 2021). "Moreover, gain of function and loss of function studies showed that up-regulation of FOXN3 notably inhibited glioma cell proliferation, survival and motility, while down-regulation of FOXN3 dramatically facilitated glioma cell proliferation, survival and invasion." (PMID 34511432, 2021). "In addition, our findings demonstrated that FOXN3 over-expression triggered an obvious reduction in PCNA, CCND1, MMP9 and Vimentin expression levels in glioma cells, whereas FOXN3 ablation elicited a remarkable elevation in PCNA, CCND1, MMP9 and Vimentin expression levels." (PMID 34511432, 2021).
influenza (1 paper, 2013). An acute viral infection of the respiratory tract, occurring in isolated cases, in epidemics, or in pandemics; it is caused by serologically different strains of viruses (influenzaviruses) designated A, B, and C, has a 3-day incubation period, and usually lasts for 3 to 10 days. "Quantitation of their expression in influenza infected A549 cells showed that ANKRD52, ATP5A1, FOXN3 were downregulated whereas all the other transcripts were upregulated." (PMID 24116168, 2013).
Insulin resistance (1 paper, 2025). Increased resistance towards insulin, that is, diminished effectiveness of insulin in reducing blood glucose levels. "The FOXN3 gene, crucial for liver glucose metabolism, was hypermethylated, possibly contributing to the insulin resistance seen in these animals." (PMID 40914344, 2025).
lymphoma (1 paper, 2019). A malignant (clonal) proliferation of B- lymphocytes or T- lymphocytes which involves the lymph nodes, bone marrow and/or extranodal sites. "This study confirmed that in lymphomas, the deletion of FOXN3 leads to increased level of the target gene PIM2, thereby weakening the inhibitory effect of FOXN3 on tumor growth." (PMID 31214487, 2019).
myeloid leukemia (1 paper, 2014). A clonal proliferation of myeloid cells and their precursors in the bone marrow, peripheral blood, and spleen. "As a tumor suppressor gene, FOXN3, was singled out from the small recurrent CNA of 14q32, however, it is proved that deletion of FOXN3 is a common marker of myeloid leukemia rather than a specific marker for AML-M5 subtype." (PMID 24727659, 2014).
pancreatic cancer (1 paper, 2022). "Kaplan-Meier plotter was then used for survival analysis, revealing that high FOXN3 expression in pancreatic cancer might be associated with a poor prognosis." (PMID 36324573, 2022). "The present study aims to assess the clinicopathological value and prognostic significance of FOXN3 expression in pancreatic cancer." (PMID 36324573, 2022). "Consistently, our IHC results also confirmed that FOXN3 was highly expressed in pancreatic cancer tissue samples." (PMID 36324573, 2022). "In most cancers, forkhead box N3 (FOXN3) acts as a transcriptional inhibitor to suppress tumor proliferation, but in pancreatic cancer, the opposite effect is observed." (PMID 36324573, 2022). "Collectively, our findings reveal that FOXN3 is involved in the occurrence and progression of pancreatic cancer and may be useful as a prognostic tool in pancreatic cancer immunotherapy." (PMID 36324573, 2022). "Finally, we analyzed the relationship between FOXN3 and immune infiltration in pancreatic cancer." (PMID 36324573, 2022).
Primary immunodeficiency (1 paper, 2022). "Based on KEGG’s analysis, FOXN3 was found to be associated with cell adhesion molecules, T cell receptor signaling pathway, Primary immunodeficiency, Chemokine signaling pathway, etc.." (PMID 36324573, 2022).
psoriasis (1 paper, 2021). An autoimmune condition characterized by red, well-delineated plaques with silvery scales that are usually on the extensor surfaces and scalp. "Among the associated genes were EGR3, GATA6, GATA3, and FOXN3, which play important roles in psoriasis." (PMID 34068434, 2021). "FOXN3, regulating cell differentiation and cell cycle, is down-regulated along with GATA3 in psoriasis." (PMID 34068434, 2021).
testis tumors (1 paper, 2016). "The function of FOXN3 has never been linked to testis tumors or male sterility." (PMID 27281616, 2016).
thyroid cancer (1 paper, 2022). "Additionally, fork head box N3 (FOXN3), a key cell cycle regulator and transcriptional tumorigenesis suppressor, was also identified as a direct target of miR-574-5p in thyroid cancer progression." (PMID 36671425, 2022).
tumor (33 papers, 2011 to 2026). "We found that FOXM1, FOXP1, and FOXN3 were negatively correlated with OS and that FOXP1 and FOXN3 were positively correlated with histological grade and tumor size." (PMID 36622275, 2023). "Significant TFs identified within the enhancer regions include Fra1, TEAD3, EWS-ERG fusion, and FOXN3, which are responsible for cell growth, tumor suppression, and suppression of transcription of transforming growth factor and play a role in several cancers." (PMID 36936794, 2023). "Together, these results imply that FOXN3 is closely related to the occurrence and development of the tumor immune microenvironment in PDAC tissues." (PMID 36324573, 2022). "Forkhead box N3 (FOXN3) belongs to the forkhead box family, which takes part in multiple biological processes, such as tumor development." (PMID 35656441, 2022). "On the basis of the observations in vitro, the tumor transplantation models were established in mice through the subcutaneous inoculation of empty vector- or FOXN3 expression vector-treated U87MGcells into the flanks of mice." (PMID 34511432, 2021). "Lastly, FOXN3, a known tumor suppressor in various types of cancer, also inhibits Wnt signaling by competitive binding of β-catenin." (PMID 34298659, 2021). "In order to further analyze the impacts of FOXN3 on tumor cell proliferation, apoptosis and motility, the expression patterns of malignant phenotype-related proteins in U87MGcells and SF126 cells were also evaluated." (PMID 34511432, 2021). "On the other hand, 3 genes (ANKRD11, BCL11A, and FOXN3) out of the top 5 mythelated genes in cluster 6 are well-known in their anti-tumor action." (PMID 32272578, 2020). "The expression of forkhead box N3 (FOXN3), also known as checkpoint suppressor 1 (CHES1), is reduced in many types of tumours." (PMID 32078244, 2020). "In a related study on the T-cell leukemia tumor suppressor network, the FOXN3 gene was down-regulated in T-lymphocytic leukemia (T-ALL) significantly." (PMID 31214487, 2019). "Collectively, our findings indicate that FOXN3 functions as a tumor suppressor in HCC by downregulating the expression of E2F5." (PMID 27259277, 2016). "The weight of tumor revealed that FOXN3 inhibited HCC tumorigenesis significantly in both the subcutaneous model (P = 0.0132) and the liver orthotopic model (P = 0.0004) compared with the controls." (PMID 27259277, 2016). "For example, TXNIP (thioredoxin-interacting protein), EGR1, CBX7, HOXA9 and FOXN3 (checkpoint repressor 1) have tumor suppressor functions and are targeted by the potentially oncogenic miRNA miR-93, miR-183, miR-181b, miR-182 and miR-7." (PMID 21375733, 2011). "FOXN3 was identified as a selected candidate gene, which has been reported to be involved in cell proliferation, apoptosis, and pathogenesis in cancer, and functions as a tumor suppressor." (PMID 34944246, 2021). "Moreover, significantly smaller neoplasms were harvested from the FOXN3 over-expression group in comparison with control group (P < 0.01)." (PMID 34511432, 2021). "As a tumour suppressor, the impact of FOXN3 on prognosis has been demonstrated in solid tumours." (PMID 32078244, 2020). "We then asked whether upregulation of RASGRP3 or FOXN3 contribute to the tumor suppressive role of FOXA1 in NPC cells." (PMID 32201519, 2020). "In addition, in vivo xenograft assays demonstrated that FOXN3 over-expression could restrain tumor growth in the nude mice models." (PMID 34511432, 2021). "The misregulation of FOXN3 could contribute to both spermatogenesis defects and tumor genesis." (PMID 27281616, 2016). "Therefore, whether FOXN3 promotes or inhibits tumor formation might be determined by the tissue context." (PMID 27281616, 2016). "Recent research demonstrated that miR-183-5p can increase HCC cell proliferation by suppressing the expression of tumor suppressors (including AKAP12, DYRK2, FOXN3, FOXO1 and LATS2) which is agreement with our results." (PMID 37168369, 2023).
tumor (continued). "Therefore, FOXN3 may play an important role in the tumor immune microenvironment of PDAC." (PMID 36324573, 2022). "Also, this suggests that FOXN3 may be an important tumor suppressor gene." (PMID 31214487, 2019). "In the present work, we explore the expression profiles of FOXN3 in HCC and describe a biochemical and genetic interaction between FOXN3 and E2F5, which was originally identified based on its ability to act as a tumor suppressor in HCC." (PMID 27259277, 2016). "A recent study in a cancer cell line indicated that CHES1/FOXN3 decreases cell proliferation by repressing PIM2 and protein biosynthesis, suggesting that FOXN3 is a potential tumor suppressor." (PMID 27281616, 2016). "The most down-regulated genes, FOXO1, FOXN3, and FOXP2, were highly expressed in non-tumor cells, indicating that tumor patients may have an inhibition of the normal cellular function." (PMID 41584858, 2026). "Furthermore, menin can also suppress tumorigenesis of the endocrine pancreas through its interactions with the transcription factors CHES1/FOXN3 and JunD in β-cells and islet tumor cells." (PMID 39336822, 2024). "To functionally test whether FOXN3 and RUNX1 promoted or inhibited distinct tumor states, we performed two separate experiments." (PMID 36473848, 2022). "Similarly to FOXO3/4, FOXN3 overexpression decreases β-catenin/TCF7L2 interaction in CRC cell lines, and depletion of FOXN3 increased tumor growth and metastasis in mice." (PMID 34298659, 2021). "However, the upregulated methylation levels of FOXC2, FOXF1, FOXF2, FOXM1, and FOXN3 indicated that an epigenetic mechanism was not the main reason for the elevated FOX expression in tumor tissues." (PMID 36622275, 2023). "However, the specific functions of FOXN3 in the cells of mammals, including humans, and its mechanisms of action in tumor cells have not yet been clearly confirmed." (PMID 31214487, 2019). "As a transcription regulator, FOXN3 has been reported to inhibit the expression of some tumour oncogenes, such as PIM2 and E2F5.9, 34 However, the negative correlation between FOXN3 and PIM2 or E2F5 was not validated in this study." (PMID 32078244, 2020).
cancer (27 papers, 2012 to 2025). A tumor composed of atypical neoplastic, often pleomorphic cells that invade other tissues. "Subsequently, immune infiltration analysis was performed on TISBD, and FOXN3 was found to be significantly associated with TIICs in PDAC when compared to other cancers." (PMID 36324573, 2022). "In OC, transcriptional expression of RPS15A is inhibited by FOXN3, which suppresses cancer progression." (PMID 40000433, 2025). "TISIDB was used to analyze the relationship between FOXN3 expression and TIICs in pan-cancer samples." (PMID 36324573, 2022). "And we used qRT-PCR to understand the mRNA expression level of FOXN3, and the results showed that FOXN3 expression was significantly increased in cancer tissues compared with normal pancreatic tissues." (PMID 36324573, 2022). "In the previous studies, FOXN3 has been proved as a key player during the malignant development of varied kinds of malignant tumors." (PMID 34511432, 2021). "Consistent with studies of FOXN3 in other cancers, these results imply that FOXN3 plays a key role in the development of HCC." (PMID 27259277, 2016). "This evidence implies that FOXN3 plays a role in cell proliferation, apoptosis and pathogenesis in human cancer by regulating other genes as a transcription factor." (PMID 27259277, 2016). "FOXN3 is involved in cell cycle regulation and its expression decreased in many types of cancers." (PMID 36768681, 2023). "FOXN3 depletion abrogated MAGI2-AS3-mediated anti-cancer action." (PMID 35656441, 2022). "FOXN3 is a member of the forkhead box family, which has a similar DNA-binding domain and is involved in organ differentiation, development, cell growth, and cancer." (PMID 36324573, 2022). "Previous studies revealed that FOXN3 could regulate other genes as a transcription factor in a variety of cancers." (PMID 36324573, 2022). "In consistent with observations in other cancers, FOXN3 mRNA level is decreased in NPC samples." (PMID 32201519, 2020). "The candidate FOXN3 is a key gene of the Wnt/β-Catenin pathway that is altered in cancers." (PMID 30102725, 2018). "FOXN3 is a member of the FOX protein family, which has been studied in the liver, thyroid, breast, and other cancers." (PMID 36324573, 2022). "MAGI2-AS3 functioned as a cancer suppressor and enforced expression of MAGI2-AS3 inhibited growth, glycolysis, and triggered apoptosis of ALL cells by sponging miR-452-5p to enhance FOXN3 expression." (PMID 35656441, 2022). "Additionally, even though we can now infer that the FOX co‐expression relationships are globally disrupted in cancer tissues, it is still unclear how the centric FOX regulators shifted from normal (FOXN3 and FOXJ2) to cancer (FOXL1 and FOXD4L)." (PMID 37401400, 2023). "By integrating patterns of FOX genes expression with anticancer drugs sensitivity, we speculated that six FOX genes, including FOXO3, FOXO1, FOXN3, FOXK2, FOXN2, and FOXJ3, might be important for the development and treatment of a wide range of cancers." (PMID 36292640, 2022). "In the present study, we demonstrate that FOXN3 expression is significantly downregulated in several cancer tissues compared with adjacent non-cancerous tissues, including oral squamous cell carcinoma and laryngeal carcinoma." (PMID 27259277, 2016). "Forkhead box N3 (FOXN3) is an important member of the FOX family of transcription factors that plays an essential role in several cancers but has not been investigated in HCC." (PMID 27259277, 2016).
renal disease (1 paper, 2023). "We also found novel cell-type-specific TFs, such as Nr1h4 for PTinj_1, Nfyc for DediffPT_1, and Foxn3 for PTinj_2, which are interesting candidates for studying their roles in renal disease development and warrant validation in future studies." (PMID 37023747, 2023).
FOXN3 also shares sentences with these, for which no sentence is quoted: osteosarcoma (3 papers); acute lymphoblastic leukemia (2); mental disorder (2); amyotrophic lateral sclerosis (1); attention deficit-hyperactivity disorder (1); autism spectrum disorder (1); Azoospermia (1); bipolar disorder (1); Bladder Urothelial Carcinoma (1); Breast invasive carcinoma (1); cervical squamous cell carcinoma (1); clubfoot (1); diffuse large B-cell lymphoma (1); eating disorder (1); endocervical adenocarcinoma (1); hairy cell leukemia (1); Hodgkins lymphoma (1); infection (1); laryngeal carcinoma (1); lentivirus infection (1); major depressive disorder (1); Marfan syndrome (1); nasopharyngeal carcinoma (1); nervous system tumors (1); ovarian carcinoma (1); pancreatic adenocarcinoma (1); prostate carcinoma (1); renal cell carcinoma (1); schizophrenia (1); T-cell acute lymphoblastic leukemia (1).
A further 4 diseases each share a sentence with FOXN3 in 1 paper.